RASSF10 (Ras association domain family member 10)
Description:
Plays an important role in regulating embryonic neurogenesis.
Tractability: No criterion of Open Targets' tractability assessment is met for any kind of drug.
Gene: Protein-coding gene on chromosome 11 (13,009,316 to 13,012,119, forward strand). Ensembl gene ENSG00000189431.
Subcellular location: Cytoplasm, cytosol; Cytoplasm, cytoskeleton, microtubule organizing center, centrosome; Cytoplasm, cytoskeleton, spindle pole
Subcellular location (Human Protein Atlas): Vesicles; Cytosol
Gene Ontology:
Molecular function: protein binding
Biological process: positive regulation of neural precursor cell proliferation; positive regulation of neurogenesis; signal transduction
Cellular component: cytosol; centrosome; spindle pole
Genetic constraint (gnomAD): Loss-of-function variants: 21 observed, 31.98 expected, observed/expected ratio (o/e) 0.66, 90% interval 0.47 to 0.95. The synonymous counts are far from expectation, so gnomAD's model fits this gene poorly and the ratio says little. Missense variants: 767 observed, 657.64 expected, observed/expected ratio (o/e) 1.17, 90% interval 1.1 to 1.24. Synonymous variants: 364 observed, 296.1 expected, observed/expected ratio (o/e) 1.23, 90% interval 1.13 to 1.34.
Homologues: Orthologues: chimpanzee RASSF10 (99% identical), macaque RASSF10 (97% identical), pig RASSF10 (90% identical), dog RASSF10 (87% identical), mouse Rassf10 (87% identical), rat Rassf10 (85% identical), guinea pig RASSF10 (81% identical), rabbit RASSF10 (76% identical), tropical clawed frog rassf10 (54% identical), zebrafish RASSF10 (50% identical), Drosophila melanogaster meru (16% identical). Paralogues in human: RASSF9 (32% identical), RASSF8 (15% identical), RASSF7 (14% identical).
Diseases named in the same sentence as RASSF10 in open-access papers:
RASSF10 is named in the same sentence as 52 diseases in open-access papers, as found by Europe PMC text mining. Sharing a sentence is not in itself a finding about the gene and the disease. The quoted sentences say what the papers report.
lung carcinoma (7 papers, 2015 to 2024). "For LRP5/6, the phosphorylation of LRP6 was decreased by RASSF10, and downregulation of RASSF10 promotes lung cancer proliferation and invasion." (PMID 38872189, 2024). "We showed the epigenetic inactivation of RASSF10 in breast cancer, lung cancer, skin cancer, and thyroid cancer and showed that RASSF10 inhibited the growth of breast cancer, pancreas carcinoma, and sarcoma cell lines." (PMID 32047266, 2020). "Depletion of RASSF10 by CRISPR/Cas9 technology induces the ability of lung cancer cells to proliferate and to invade an extracellular matrix after TGFβ treatment." (PMID 31817988, 2019). "RASSF8 and RASSF10 suppress cell proliferation, migration and invasion in gastric cancer, lung cancer, liver cancer, cervical cancer, colorectal cancer and esophageal squamous cell carcinoma." (PMID 31768130, 2019). "Epigenetic inactivation of RASSF10 through promoter hypermethylation has been reported in various tumor entities including lung cancer, thyroid cancer, melanoma and several others." (PMID 31817988, 2019). "We showed the epigenetic inactivation of RASSF10 in thyroid cancer, lung cancer, skin cancer, breast cancer and showed that RASSF10 inhibited growth of breast cancer, pancreas carcinoma and sarcoma cell lines." (PMID 31817988, 2019). "To test the interaction of ASPP2 with endogenous RASSF10 we used the RASSF10 expressing lung cancer cell line A549." (PMID 31817988, 2019). "As knockdown of RASSF10 increases mitosis in A549 lung cancer cells and we found restoration of RASSF10 induces G2/M arrest in colorectal cancer." (PMID 25638156, 2015). "Reduced RASSF10 levels further reveal a reduced survival of colon cancer, head and neck cancer patients, as well as liver cancer, lung cancer and gastric cancer patients." (PMID 31817988, 2019). "Previous studies in A549 lung cancer cells reported that knockdown of RASSF10 increases mitosis." (PMID 25638156, 2015). "It has been reported that knockdown of RASSF10 increases mitosis in A549 lung cancer cells." (PMID 26124922, 2015). "Knockdown of RASSF10 increases mitosis in A549 lung cancer cells." (PMID 25638156, 2015). "It will be interesting to study the ZAR1 hypermethylation together with other known lung cancer tumour suppressors, e.g. RASSF1A and RASSF10." (PMID 28588743, 2017).
gastric cancer (6 papers, 2016 to 2021). A primary or metastatic malignant neoplasm involving the stomach. "Downregulation of RASSF10 expression has been associated with poor survival of patients with gastric cancer." (PMID 34224728, 2021). "We therefore attempted to explore the mechanism by which RASSF10 regulates cell proliferation and survival using gastric cancer as a model system." (PMID 34224728, 2021). "RASSF10 has been reported to modulate Wnt/β-catenin signaling and Jun N-terminal kinase /c-Jun/AP-1 pathway to regulate gastric cancer progression." (PMID 34224728, 2021). "Wei and other investigators demonstrated that RASSF10 overexpression inhibits gastric carcinoma cell growth by suppressing Wnt/β-catenin signaling." (PMID 26701853, 2016). "The gene for tumor suppressor RASSF10, which encodes a protein that inhibits cell proliferation, invasion, and migration and induces apoptosis was hypermethylated in EBV-positive gastric cancer compared to EBV-negative gastric cancers." (PMID 34361112, 2021). "Furthermore, an inverse correlation was observed between RNF2 and RASSF10 expression in Indian gastric cancer cohorts." (PMID 34224728, 2021). "Consistently, a recent report suggests that the status of RASSF10 promoter methylation may serve as a valuable indicator for the diagnosis and prognosis of gastric cancer." (PMID 34224728, 2021). "Correlation analysis suggests a significant positive correlation of RASSF10 and NPM expression in gastric cancer samples with a Pearson correlation coefficient of 0.075." (PMID 34224728, 2021). "Correlation analysis clearly indicates that higher expression of RASSF10 and NPM correlates with better patient survival; in contrast, higher expression of RNF2 correlated with poor survival of patients with gastric cancer." (PMID 34224728, 2021). "Having elucidated that the critical role for the RASSF10/NPM positive feedback loop on control of cell proliferation, we next checked the clinical relevance of this regulation in gastric cancer." (PMID 34224728, 2021). "Collectively, these observations suggest the clinical significance of RASSF10, NPM, and RNF2 expression on gastric cancer prognosis." (PMID 34224728, 2021). "In conclusion, RASSF10 is an important downstream target of RNF2 and the RASSF10/NPM/GADD45a/RNF2 feedback cascade may be used as a new biomarker for diagnosis and novel drug target for the therapy of gastric cancer." (PMID 34224728, 2021). "The positive correlation of RASSF10 and NPM expression with better patient survival further suggests the positive feedback axis between RASS10 and NPM plays a critical role in controlling gastric cancer progression." (PMID 34224728, 2021). "Finally, the expression of RASSF10 and NPM positively correlated with the survival of patients with gastric cancer, and the reverse was observed with RNF2 expression, which suggests their association with gastric cancer progression." (PMID 34224728, 2021). "Interestingly, the expression of RNF2 as well as knockdown of NPM in gastric cancer cells enhance RASSF10 ubiquitination and destabilization, and the reverse was noticed with depletion of endogenous RNF2 by shRNA or ectopic expression of NPM." (PMID 34224728, 2021). "Finally, our findings provide insights into the mode of action of the RASSF10/NPM/RNF2 signaling cascade on controlling cell proliferation and may represent a novel therapeutic avenue for the prevention of gastric cancer metastasis." (PMID 34224728, 2021). "Interestingly, the Kaplan–Meier plot analysis shows a positive correlation of RASSF10 and NPM expression with greater gastric cancer patient survival and the reverse with expression of RNF2, suggesting that they may have a role in cancer progression." (PMID 34224728, 2021).
colorectal cancer (4 papers, 2015 to 2019). A primary or metastatic malignant neoplasm that affects the colon or rectum. "In this study, RASSF10 was found to be frequently methylated in human colorectal cancer with resulting loss of expression." (PMID 25638156, 2015). "In conclusion, RASSF10 was frequently methylated in human colorectal cancer and methylation of RASSF10 was associated with late tumor stage and metastases." (PMID 25638156, 2015). "RASSF10 was methylated in 60.7% (54/89) of primary colorectal cancers and was positively associated with tumor stage (p < 0.05) and metastasis (p < 0.05)." (PMID 25638156, 2015). "In conclusion, our study demonstrates RASSF10 is frequently methylated in human colorectal cancer leading to loss of expression." (PMID 25638156, 2015). "Our previous study also found that RASSF10 induces G2/M arrest in human colorectal cancer and esophageal cancer." (PMID 26124922, 2015). "The expression of MDM2 and RASSF10 was evaluated by immunohistochemistry in 27 available cases of human primary colorectal cancer." (PMID 25638156, 2015). "The expression of MDM2 is inversely correlated with RASSF10 in primary colorectal cancer (P < 0.05)." (PMID 25638156, 2015). "The results suggest that RASSF10 expression is mainly altered by promoter region methylation in colorectal cancer." (PMID 25638156, 2015). "Restoration of RASSF10 led to inhibition of colorectal cancer cell proliferation in vitro and in vivo and increased apoptosis." (PMID 25638156, 2015). "The results suggest that RASSF10 functions as a mitotic inhibitor in human colorectal cancer and sensitizes cancer cells to docetaxel." (PMID 25638156, 2015). "In 7 cases of human primary colorectal cancer with high level expression of RASSF10, the expression of MDM2 was diminished." (PMID 25638156, 2015). "The expression of RASSF10 was reduced significantly in colorectal cancer compared with adjacent tissue samples (P < 0.05)." (PMID 25638156, 2015). "RASSF10 expression was next evaluated using immunohistochemistry in 27 available colorectal cancer and matched adjacent tissue samples." (PMID 25638156, 2015). "The expression of RASSF10 was regulated by promoter regional methylation in colorectal cancer cells." (PMID 25638156, 2015). "In this study we demonstrate that restoring RASSF10 expression induced both G2/M arrest and apoptosis in colorectal cancer cells." (PMID 25638156, 2015). "As a test of whether RASSF10 expression was potentially affected by promoter region hypermethylation, these colorectal cancer cell lines were treated by 5-aza-2′-deoxycytidine (5-aza), a DNA methylation transferase inhibitor." (PMID 25638156, 2015). "RASSF10 is a mitosis inhibitor whcih sensitized colorectal cancer cells to docetaxel." (PMID 25638156, 2015).
colorectal cancer (continued). "Since we have demonstrated tumor suppressor functions for RASSF10, reversal of RASSF10 repression may potentially be an approach for colorectal cancer therapy." (PMID 25638156, 2015). "However, none of these mutations explain the loss of RASSF10 expression and mutation of RASSF10 appears to be a rare event in human colorectal cancer." (PMID 25638156, 2015). "RASSF10 methylation may also serve as a marker of poor prognosis of colorectal cancer." (PMID 25638156, 2015). "However, the epigenetic change and the function of RASSF10 in colorectal cancer remains unclear." (PMID 25638156, 2015). "Since docetaxel is a microtubule inhibitor which is most effective in mitotic phase, we found that sensitivity of colorectal cancer cells to docetaxel was indeed increased in RKO and HCT116 when RASSF10 expression was restored." (PMID 25638156, 2015). "The expression of cdc-2 and cyclin B1 was reduced after re-expression of RASSF10 in RKO and HCT116 cells, providing a mechanism by which RASSF10 induces G2/M arrest in colorectal cancer." (PMID 25638156, 2015).
hepatocellular carcinoma (4 papers, 2015 to 2016). A malignant tumor that arises from hepatocytes. "RASSF10 is methylated in 82.6% of human primary hepatocellular carcinoma cells (HCC) and methylation of RASSF10 is associated with tumor size and TNM stage." (PMID 26703582, 2015). "Here, we examined RASSF10 expression in hepatocellular carcinoma (HCC) and its role in hepatocarcinogenesis." (PMID 26701853, 2016). "Here, we examined RASSF10 for the biological functions and related molecular mechanisms in hepatocellular carcinoma (HCC)." (PMID 27348267, 2016).
liver cancer (4 papers, 2016 to 2019). An epithelial or non-epithelial malignant neoplasm that arises from the liver. "We found that low RASSF10 expression was associated with tumor differentiation, hepatocirrhosis, Barcelona Clinic Liver Cancer (BCLC) stage and tumor thrombus." (PMID 26701853, 2016). "In patient tissues, low RASSF10 levels correlated with hepatocirrhosis, poor tumor differentiation, tumor thrombus and Barcelona Clinic Liver Cancer stage, and were indicative of increased tumor recurrence and reduced patient survival." (PMID 26701853, 2016). "The putative tumor suppressor function of RASSF10 in liver cancer was verified by in vitro and in vivo assays." (PMID 27348267, 2016).
malignant melanoma (4 papers, 2013 to 2024). "Our earlier studies observed the same increasing methylation pattern from naevi to primary tumors and cell lines for another tumor suppressor such as RASSF10 in malignant melanoma." (PMID 38397165, 2024). "RASSF10 was shown to be hypermethylated at its CpG island promoter region in various tumor types for instance malignant melanoma." (PMID 24252868, 2013).
breast carcinoma (3 papers, 2016 to 2020). "In breast cancer we can show that high RASSF10 methylation is associated with reduced RASSF10 expression, we observed that loss of RASSF10 expression correlates with progressed breast cancer grade and reduced overall survival of breast cancer patients." (PMID 31817988, 2019). "Further larger samples numbers will clarify, if RASSF10 methylation could be utilised as a prognostic tool in early breast cancer detection, predicting prognosis and susceptibility to chemotherapeutic response." (PMID 26927176, 2016). "Our study shows that RASSF10 is expressed in normal breast but inactivated by methylation in breast cancer." (PMID 26927176, 2016). "In this present study we mainly focussed on the contribution of RASSF10 promoter methylation in breast cancer." (PMID 26927176, 2016). "Next we aimed to understand how RASSF10 exerts its growth inhibition in breast cancer cell lines and performed apoptosis and cell cycle analysis." (PMID 26927176, 2016). "Further reexpression of RASSF10 in two RASSF10 methylated breast cancer cell lines blocked tumour growth in colony formation analysis." (PMID 26927176, 2016). "Our present work additionally shows that inhibition of DNA methylation (by blocking DNMT action using Aza) in breast cancer cell lines reverses RASSF10 promoter methylation." (PMID 26927176, 2016). "We therefore conclude that RASSF10 induced apoptosis in the RASSF10 hypermethylated breast cancer cell lines MCF7 and T47D." (PMID 26927176, 2016). "Human breast cancer cell lines are strongly methylated for the RASSF10 promoter, and methylation levels vary." (PMID 26927176, 2016). "RASSF10 is inactivated in 63% of primary breast cancer samples but only 4% of normal control breast tissue is methylated (p < 0.005)." (PMID 26927176, 2016). "We were therefore interested in studying RASSF10 in breast cancer and analysed normal vs. cancerous primary tissues." (PMID 26927176, 2016). "Future studies will clarify the mechanisms of RASSF10 tumour inhibition in breast cancer in detail." (PMID 26927176, 2016). "Additionally we studied demethylation and reversal of RASSF10 expression as well as RASSF10’s tumour suppressive function in breast cancer." (PMID 26927176, 2016). "In this study we analysed the promoter inactivation by DNA methylation of RASSF10 in breast cancer." (PMID 26927176, 2016). "Furthermore RASSF10 was characterised by the ability to block growth of breast cancer cell lines by apoptosis induction." (PMID 26927176, 2016). "Interestingly more than 80% of breast cancer samples harboured a hypermethylation of RASSF10 and/or RASSF1A promoter." (PMID 26927176, 2016). "We next studied primary breast cancer samples regarding a RASSF10 and RASSF1A promoter methylation." (PMID 26927176, 2016). "This demethylation was accompanied by reexpression of RASSF10 in those breast cancer cell lines." (PMID 26927176, 2016). "In summary, we could show that RASSF10 induces apoptosis in breast cancer cell lines and therefore exhibits its growth inhibitory potential as a tumour suppressor." (PMID 26927176, 2016). "Furthermore we tested the tumour suppressive function of RASSF10 in three breast cancer cell lines." (PMID 26927176, 2016). "Breast cancer cell lines MCF7 and T47D were chosen for further analysis due to the present RASSF10 promoter methylation." (PMID 26927176, 2016). "In our study we analysed the inactivating promoter methylation status of RASSF10 and RASSF1A in breast cancer by COBRA and pyrosequencing analysis, as well as its implications in tumour growth by colony formation." (PMID 26927176, 2016). "Demethylation treatment of breast cancer cell lines MCF7 and T47D reversed RASSF10 promoter hypermethylation and re-established RASSF10 expression." (PMID 26927176, 2016). "In addition, we could show the growth inhibitory potential of RASSF10 in breast cancer cell lines MCF7 and T47D upon exogenous expression of RASSF10 by colony formation." (PMID 26927176, 2016).